APOE (apolipoprotein E)
Diseases named in the same sentence as APOE in open-access papers (continued):
Sharing a sentence is not in itself a finding about the gene and the disease.
diabetes (continued). "The ApoE Ɛ4 allele and its genotypes (Ɛ3/Ɛ4 and Ɛ4/Ɛ4) were linked to a higher risk of type 2 diabetes mellitus by changing the way fats are broken down." (PMID 39138505, 2024). "In univariate analysis, smoking, diabetes, total cholesterol, ApoE, FFA, FT4, and TT4 were significantly associated with CSFP." (PMID 38787982, 2024). "In this study, overweight (BMI ≥ 24.0 kg/m2), history of smoking, diabetes mellitus, APOE ɛ3/ɛ4 genotype, and APOE ɛ4 allele were independent risk factors for coronary atherosclerosis in patients with hypertension." (PMID 39261765, 2024). "The apolipoprotein E genotype (ɛ4 carriers, ɛ2 carriers and ɛ3/ɛ3 homozygotes) and vascular risk factors (age, hypertension and diabetes) were considered predictors." (PMID 39007039, 2024). "In the present study, we investigate the pathology and molecular mechanisms underlying cardiac dysfunction induced by diabetes and dyslipidemia in ApoE KO mice." (PMID 38390337, 2024). "First, AD and cardiovascular diseases share multiple risk factors, including hypercholesterolemia, APOE status, diabetes mellitus, and obesity." (PMID 38489178, 2024). "The ApoE ɛ2 allele has been associated with a decreased likelihood of developing diabetes; however, the ApoE ɛ4 allele has specifically been linked to impaired glucose tolerance and insulin resistance." (PMID 37123009, 2023). "Individuals with APOE e2 and APOE e4 genotypes had distinct microbiota composition, and higher level of pro-inflammatory microbiota were associated higher BMI and diabetes." (PMID 37736325, 2023). "Older age, male sex, lower education, Black race, APOE ε4 alleles, and diabetes were associated with higher odor identification errors and higher anosmia prevalence, and greater physical activity and hypertension with better olfaction." (PMID 37630831, 2023). "We detected significant associations between gut microbial community structure with APOE genotype, BMI, diabetes, and hypertension in our community dwelling older adult cohort." (PMID 37736325, 2023). "Further studies are required to completely understand the function of ApoE polymorphisms in the pathogenesis of diabetes and to consider possible therapeutic approaches that target this pathway." (PMID 37123009, 2023). "The HR was adjusted for age, sex, race and ethnicity, education, comorbidities (e.g., diabetes), smoking, and the presence of APOE e4 allele (i.e., a gene indicating an increased risk of Alzheimer’s and an earlier age of disease onset)." (PMID 37834986, 2023). "Age at time of scan, gender, ethnicity, education, BMI, diabetes, mean cognitive z-score, presence of APOE ε4 allele, caloric intake, hypertension, heart disease, and stroke." (PMID 37513622, 2023). "Age, gender, education, participation in cognitive activities, total energy intake (kcal), time, and the interaction between time and each covariate, physical activity, presence of APOE ε4 alleles, depression, hypertension, diabetes, and stroke." (PMID 37513622, 2023). "Risk factors associated with development of AD involve genetic predisposition (familial early-onset forms), allele ApoE-4 for apolipoprotein E, age, sedentarism, hypertension, diabetes, and metabolic syndrome, among others." (PMID 37818457, 2023). "Energy intake, age, sex, presence of APOE ε4 allele, education, mental activity, physical activity, smoking status, depression, diabetes, BMI, hypertension, heart disease, and stroke." (PMID 37513622, 2023). "Potential modifiable risk factors include apolipoprotein E (APOE) ε4, hypertension, obesity, smoking, diabetes, depression, cardiovascular disease, head injury, and social isolation." (PMID 37060077, 2023). "Although some studies have examined the association between ApoE polymorphisms and the risk of type 2 diabetes mellitus (T2DM), the findings differ depending on the location and population." (PMID 37123009, 2023).
diabetes (continued). "When assessing for a diabetes × cognition interaction, a significant association between ccf-8oxoG variant count and both population and APOE was determined." (PMID 36993752, 2023). "For CL cutoff-based Aβ positivity, decreased BMI (OR = 1.56, 95% CI 1.06–2.29) was associated with a greater risk of Aβ positivity after controlling for age, sex, APOE e4 genotype, years of education, hypertension, diabetes, baseline BMI, and BMI variability." (PMID 35936766, 2022). "Nonetheless, the precise mechanisms by which the APOE genotype and diabetes contribute to AD risk are still undetermined." (PMID 36153580, 2022). "It is important to note that these studies examining the influence of apoE polymorphisms on diabetes were conducted with animals fed a high fat diet." (PMID 36077289, 2022). "Higher BMI variability (OR = 2.12, 95% CI 1.28–3.51) was associated with a greater risk of Aβ positivity after controlling for age, sex, APOE e4 genotype, years of education, hypertension, diabetes, baseline BMI, and BMI change." (PMID 35936766, 2022). "Decreased BMI (odds ratio [OR] = 1.68, 95% confidence interval [CI] 1.16–2.42) was associated with a greater risk of Aβ positivity after controlling for age, sex, APOE e4 genotype, years of education, hypertension, diabetes, baseline BMI, and BMI variability." (PMID 35936766, 2022). "Sporadic AD accounts for most cases (~95%) and risk factors include age, diabetes, cardiovascular disease, education level, maternal history, and polymorphisms in the Apolipoprotein E (APOE, chromosome 19) gene." (PMID 36012480, 2022). "APOE polymorphisms and its risk associations with coronary artery disease, hypertension, diabetes, and carotid arterial atherosclerosis are widely debated." (PMID 35154509, 2022). "A greater BMI variability (OR = 1.73, 95% CI 1.07–2.80) was associated with a greater risk of Aβ positivity after controlling for age, sex, APOE e4 genotype, years of education, hypertension, diabetes, baseline BMI, and BMI change." (PMID 35936766, 2022). "Risk factors for AD mainly include advanced age, family history, diabetes, middle-aged hypertension, smoking, alcohol consumption, apolipoprotein E (apoE) Ɛ4 allele, depression, physical inactivity, and low educational achievement." (PMID 36497772, 2022). "For example, the role of Apolipoprotein E in lipid metabolism has been well established, APOE was also reported to be associated with the risk of cardiovascular diseases and diabetes mellitus, and APOE is the most replicated longevity‐related gene." (PMID 35754110, 2022). "Several other factors confer increased risk including apolipoprotein E ε‐4 (APOE4) genotype, stroke and vascular risk factors, head trauma, diabetes mellitus (DM), and obesity." (PMID 35128745, 2022). "No other variables included in the multiple linear regression model demonstrated associated statistical significance (BMI, APOE, diabetes, cognition, age, population × education)." (PMID 35927256, 2022). "Most AD cases develop sporadically, associated with risk factors such as aging, the presence of ApoE allele ε4, diabetes, and metabolic syndrome, among others." (PMID 35743229, 2022). "The etiology of late-onset AD is more complex and encompasses genetics, the strongest one being the epsilon four allele of the apolipoprotein E (ApoE4) gene, as well as other factors such as obesity, diabetes, depression and hypertension." (PMID 35453527, 2022). "Most studies controlled for important confounders that influence both diet and neurocognition, as eight controlled for education, six controlled for APOE E4 status, and eight controlled for ≥1 measure of cardiovascular risk (i.e., diabetes, hypertension)." (PMID 35571887, 2022). "In this study, we investigated the etiology of ARHL in apolipoprotein E (ApoE)-deficient mice with diabetes and dyslipidemia." (PMID 36408520, 2022).
diabetes (continued). "Individuals with diabetes were shown to be more prone to extensive vascular pathology, which independently or combined with AD-type pathology (especially in APOE e4 carriers) results in a higher risk for dementia." (PMID 34867762, 2021). "Fewer years of education, the presence of the APOE E4 allele, traumatic brain injuries, obesity, diabetes, metabolic syndrome, hypertension and unhealthy diet are considered risk factors of cognitive decline." (PMID 34061901, 2021). "The presence of ApoE ε4 polymorphism combines synergistically with atherosclerosis, peripheral vascular disease or diabetes, which all contribute to an increased risk of cognitive decline, particularly AD." (PMID 33430178, 2021). "Systemic administration of let-7d mimetics into diabetic ApoE-/- mice decreased inflammatory genes, suggesting a protective role of let-7d in diabetes-associated atheroscleorsis." (PMID 34083573, 2021). "Pearson's correlation coefficients between NP scores and cognitive composite scores were calculated controlling for sex, education, hypertension, diabetes, and APOE ε4 allele." (PMID 34268331, 2021). "The ARIC study found that in both AA and nHW participants, women were 1.7 times more likely than men to be globally FBP positive after adjustment for age, race, education, APOE-ε4 allele status, hypertension, and diabetes." (PMID 34366799, 2021). "The only traits showing some evidence for shared effects across APOE and polygenic risk are several reticulocyte measures, including reticulocyte percentage and count, Aspartate aminotransferase and diabetes." (PMID 34301914, 2021). "The apolipoprotein E (APOE) gene polymorphisms have been intensively studied in patients with type 2 diabetes mellitus (T2DM) and ischemic stroke (IS) in recent years." (PMID 33490286, 2021). "Adjusted for age, gender, educational levels, APOE ε4 alleles, comorbidities (history of coronary heart disease, history of stroke, hypertension, diabetes mellitus, dyslipidaemia) and glomerular filtration rate." (PMID 34794413, 2021). "Gene therapy with secretoneurin, a CgC-derived peptide, stimulates postischemic neovascularization in apolipoprotein E-deficient mice and streptozotocin-induced diabetic mice, and improves diabetic neuropathy in db/db mice." (PMID 34204153, 2021). "Evidence has shown that sociodemographic (e.g., age, sex, and education), genetic (e.g., APOE ε4 allele), behavioral (e.g., smoking, physical inability), and metabolic factors (e.g., obesity, diabetes) are related to impaired olfaction among older people." (PMID 33912022, 2021). "Waist-to-hip ratio, diabetes, heavy smoking, hypercholesterolemia and homozygous APOE ε4 status are important risk factors, beyond hypertension, associated with WMH total burden and warrant careful control across ageing." (PMID 32971464, 2020). "When the analysis was adjusted for age and fully adjusted (age, sex, education, APOE ε4, BMI, and diabetes at baseline), the association remained significant." (PMID 33220711, 2020). "The study aimed to investigate the aberration of brain spontaneous activity and synchronization in type 2 diabetes mellitus (T2DM) patients homozygous for the apolipoprotein E (APOE)-ε3 allele." (PMID 32612525, 2020). "An association between diabetes, ApoE genotype, and dementia has been identified in Polynesian/American men, but the degree of islet amyloidosis was not determined." (PMID 32503113, 2020). "The induction of diabetes in apoE KO mice was associated with a 2-fold increase, and feeding of a western diet a 3-fold increase in plasma cholesterol levels above that seen in control apoE KO mice." (PMID 32581831, 2020). "For both C57BL/6 and apoE KO mice, the induction of diabetes was associated with a marked reduction in body weight compared to their chow fed counterparts (p < 0.0001), consistent with previous studies." (PMID 32581831, 2020).
diabetes (continued). "Risk factors, such as aging, lifestyle, obesity, or diabetes, or genetic factors such as carrying the allele ε4 in the apolipoprotein E (ApoE) gene predispose individuals to SAD development." (PMID 33233678, 2020). "Diabetes was also associated with extracellular matrix accumulation in both strains, and western diet feeding to a lesser extent in apoE KO mice." (PMID 32581831, 2020). "The APOE risk allele (T) for PDFF is associated with a higher risk of diabetes, and lower risk of cardiovascular disease and elevated LDL cholesterol in independent GWASs." (PMID 32247823, 2020). "Prospective studies that take into account important comorbid factors, such as hypertension, diabetes, and coronary artery disease, are also needed to fully elucidate the relationship between APOE E4 and GSD risk." (PMID 31200656, 2019). "Fully adjusted multivariable models found that higher age and APOE*4 carriage were both associated with more decline on both cognitive outcomes, and that diabetes was associated with more decline in MMSE score." (PMID 31335910, 2019). "Only the association of glucose to greater CD was attenuated when adjusting for diabetes, as expected; and the association of myristoylcarnitine with lower CD arose when further adjusting for ApoE‐ε4 status and physical activity (OR = 0.81)." (PMID 31218777, 2019). "Some researchers have reported that diabetes and the APOE ε4 allele interact to impact cognitive function." (PMID 30984391, 2019). "Other factors independently associated with poorer performance were APOE*4 carriage, depression, diabetes, current smoking, and history of stroke." (PMID 31335910, 2019). "A number of risk factors have been associated with AD, including the E4 allele of the apolipoprotein E (Apo-E), diabetes, vascular pathology, neuroinflammation, and infections." (PMID 31133680, 2019). "In the experimental model of streptozotocin-induced diabetes in apolipoprotein E-deficient mice, treatment with tBHQ increased Nrf2 activity in macrophages and vascular smooth muscle cells within atherosclerotic lesions." (PMID 30108504, 2018). "Age, education, MMSE score, alcohol drinking, APOE-ε4 allele, history of heart disease, diabetes, stroke, anxiety, and depression were found to be significantly different across groups with different diagnosis of cognition." (PMID 30233479, 2018). "Accordingly, some consider the ApoE−/− streptozotocin model to be the most appropriate mouse model to study accelerated diabetes-associated atherosclerosis." (PMID 30271984, 2018). "This study performed fasting blood sugar (FBS) and blood pressure measurements and investigated the presence of the ε4 allele of apolipoprotein E (APOE4) to determine the prevalence of diabetes, hypertension and the genetic risk of NCDs." (PMID 30205523, 2018). "Our novel results suggest that WMH growth was greater in those with diabetes and a higher HbA1c, but only in those who possessed an APOE e4 allele, though only the former interaction survived FDR correction." (PMID 28324763, 2017). "The association between APOE gene variants and other cardio-vascular risk factors, such as obesity, diabetes and the metabolic syndrome has also been studied in different ethnic groups." (PMID 28727855, 2017). "Further group-wise analysis showed that participants with diabetes, or high HbA1c, who carried the APOE e4 allele exhibited significantly greater change in WMH volume progression over 3.7 years than all other groups (all t-values >2.34)." (PMID 28324763, 2017). "In a previous study with a community sample of elderly Han Chinese individuals, we showed a potential association between the APOE ε3/ε3 genotype and increased susceptibility to diabetes." (PMID 29233125, 2017).
diabetes (continued). "More importantly, although the current total sample is relatively large, the proportion of individuals with both diabetes and the e4 allele was small, thus the specific diabetes-APOE interaction effect should be tested independently." (PMID 28324763, 2017). "In conclusion, our research is the first study to report that elders of Han ethnicity with the ε3/ε3 genotype are more likely to suffer from diabetes, and that the APOE ε2 allele is a possible protective factor for diabetes and blood lipids." (PMID 26998902, 2016). "Nevertheless, for both diabetes and 25-hydroxyvitamin D more research is required to elucidate the biological pathway underlying their associations with genetic variation in APOE." (PMID 27540764, 2016). "The aim of this study was to investigate the association between APOE genotype, diabetes, and plasma glucose and lipid levels." (PMID 26998902, 2016). "Our research first proposed that fasting plasma glucose was higher in the elderly population carrying the APOE ε4 allele and that the incidence of diabetes by subjective report in this group was also higher." (PMID 26998902, 2016). "This association is independent of life-course predictors of aging and death such as possession of the e4 allele of APOE, education, childhood IQ, social class, diabetes, high blood pressure, and cardiovascular disease." (PMID 25633388, 2015). "After further adjustments for childhood IQ, education, social class, hypertension, diabetes, cardiovascular disease, and APOE e4 status, there is a 16% increased mortality risk for those with a 5-year higher Δage." (PMID 25633388, 2015). "In an attempt to combine the effects of two severe clinical risk factors (dyslipidemia and diabetes) for renal disease, we used the hyperlipidemic diabetic apolipoprotein E-deficient (apoE−/−) mouse in our study." (PMID 26388784, 2015). "When diabetes is induced in apoE-deficient, a marked increase in plasma cholesterol levels is observed in diabetic mice compared to non-diabetic controls fed the same diet." (PMID 25661015, 2015). "Epidemiological studies have shown that AD and CVD share common risk factors such as hypertension during midlife, diabetes mellitus, smoking, apolipoprotein E (ApoE) ε4 isoforms, hypercholesterolemia, homocysteinemia, and, in particular, age." (PMID 25385447, 2014). "APOE gene polymorphism is known to be closely related to cardiovascular disease, hypertension, dyslipidemia, diabetes, and metabolic syndrome." (PMID 25356596, 2014). "Most importantly, the association of cognitive function with diabetes was adjusted for a large number of well-defined and well-measured cardiovascular risk factors as well as APOE ε4 carriership." (PMID 24367577, 2013). "Diabetes caused a significant increase in the amount of nitrotyrosine immunostaining in the aortic sinus region of ApoE/GPx1 dKO mice (P<0.05)." (PMID 23874911, 2013). "Cognitive engagement and physical activities have been associated with decreased risk of AD, while diabetes, epsilon 4 allele of the apolipoprotein E gene (APOE ε4), smoking, and depression have been associated with increased risk of AD." (PMID 23865055, 2013). "In diabetes mellitus, ApoE gene polymorphism was also explored, and it has proved that the Qi-Yin deficiency ZHENG in type 2 diabetes mellitus patients with macroangiopathy is associated with the ApoE E4 and E3 genotypes." (PMID 23853666, 2013). "The ε4 isoform of the APOE gene is the greatest genetic risk factor for sporadic, late onset AD, and is also associated with risk for type 2 diabetes mellitus (T2DM)." (PMID 21347323, 2011). "This small islet mass partially explains the susceptibility of B6.apoE-/- mice to diet-induced diabetes." (PMID 22204493, 2011). "Surprisingly few studies have addressed the association between the APOE polymorphism and risk of diabetes." (PMID 21941641, 2011).